RN7SKP251 (RN7SK pseudogene 251)
Gene: Miscellaneous RNA gene on chromosome 5 (68,970,439 to 68,970,752, reverse strand). Ensembl gene ENSG00000276309.
Homologues: Paralogues in human: RN7SKP180 (74% identical), RN7SKP77 (73% identical), RN7SKP79 (73% identical), RN7SKP133 (73% identical), RN7SKP255 (73% identical), RN7SKP86 (73% identical), 7SK (72% identical), RN7SKP1 (72% identical), RN7SKP124 (72% identical), RN7SKP203 (72% identical), RN7SKP202 (72% identical), RN7SKP9 (72% identical), and 284 more.